UGT1A1 (UDP glucuronosyltransferase family 1 member A1)
Diseases named in the same sentence as UGT1A1 in open-access papers (continued):
Sharing a sentence is not in itself a finding about the gene and the disease.
cholelithiasis (13 papers, 2009 to 2025). The presence of crystallized deposits forming in the gallbladder or biliary tree, primarily composed of cholesterol, bilirubin, and bile. "Genes such as ABCG5/G8, ABCB4, ABCB11, and UGT1A1 are crucial in increasing the lithogenicity of bile and are strongly associated with various forms of cholelithiasis, especially cholesterol-based." (PMID 40149408, 2025). "SNPs in the ANXA2, TEK and TGFBR3 gene loci were associated with stroke risk, the TGF-β/BMP pathway is associated with several SCD subphenotypes, while polymorphisms within the UGT1A1 are associated with increased serum bilirubin levels and cholelithiasis." (PMID 34071035, 2021). "The most frequent genetic factor linked to cholelithiasis in SCD was UGT1A1 enzyme, which is responsible for bilirubin glucuronidation into a water‐soluble form to be excreted in bile." (PMID 34584966, 2021). "UGT1A1 genotyping is therefore a potentially useful tool for identifying individuals with hemoglobinopathy at high risk of cholelithiasis and requiring close clinical monitoring." (PMID 24204915, 2013). "We analyzed the polymorphism A(TA)nTAA at the UGT1A1 promoter and the relationships between the various A(TA)nTAA genotypes and alleles and bilirubin levels and occurrence of cholelithiasis." (PMID 24167350, 2013). "Therefore, this study confirms that, in the case of unstable variants, UGT1A1 genotyping is a useful tool for identifying individuals with hemoglobinopathy at high risk of cholelithiasis and requiring close clinical monitoring." (PMID 32751969, 2020). "Our analysis shows that UGT1A1 is the major regulator of bilirubin levels in African Americans with sickle cell anemia, and that genetically mediated differences in bilirubin conjugation play an important role in cholelithiasis risk in these patients." (PMID 22558097, 2012). "Besides, other studies have shown the correlation of cholelithiasis and A(TA)7TAA variant of UGT1A1 promoter with chronic hemolytic diseases such as thalassemia minor, which represent a risk factor for cholelithiasis and the Gilbert mutation further increases this risk." (PMID 24167350, 2013). "The coincidence of UGT1A1 and ABCG8 gene mutations increases the risk of cholelithiasis in patients with hemolytic diseases." (PMID 40149408, 2025). "We further evaluated the contribution of UGT1A1 genotype to unconjugated hyperbilirubinemia and to the prevalence of cholelithiasis." (PMID 24204915, 2013). "Our study included patients with bTH and SCA and confirmed genetic risk factors for cholelithiasis in SCA, provided information about all the UGT1A1 genotypes identified and strongly suggested that UGT1A1 promoter polymorphism is a significant non-globin genetic modifier in these cases." (PMID 24204915, 2013). "The risk of developing cholelithiasis is significantly associated with older age, lower total hemoglobin level, lower hemoglobin F level, higher total serum bilirubin level, higher reticulocytes count, and UDP‐glucuronosyltransferase‐1A1 enzyme (UGT1A1) promoter polymorphism." (PMID 34584966, 2021). "Thus, not cholelithiasis but total serum bilirubin was influenced by UGT1A1 polymorphism in this SCA cohort." (PMID 26543529, 2015). "Comparisons of genotype frequencies for UGT1A1 and MDR1 2677 between patients with and without incident cholelithiasis and/or nephrolithiasis." (PMID 26360703, 2015).
Obesity (12 papers, 2015 to 2025). Accumulation of substantial excess body fat. "Some published work has demonstrated that the glucuronyl UGT1A1 enzyme that conjugates bilirubin is elevated in obesity, causing a reduced bilirubin plasma half-life and lowering circulating levels." (PMID 39873298, 2025). "People with Gilbert’s polymorphism (UGT1A1*28) exhibited significantly lower plasma proinflammatory cytokines, triglycerides, and cholesterol levels, and reduced obesity rates." (PMID 39873298, 2025). "Some studies have demonstrated that the glucuronyl UGT1A1 enzyme that clears bilirubin from the blood increases in the liver with obesity." (PMID 36671031, 2023). "Some studies have proposed that the glucuronyl UGT1A1 enzyme that clears bilirubin from the blood increases in the liver with obesity." (PMID 36671031, 2023). "An approach being investigated is the suppression of the hepatic UGT1A1 for increasing the half-life of circulating bilirubin as a possible means of treating obesity." (PMID 36671031, 2023). "Furthermore, the serum albumin and the expression of CYP3A4 decrease with obesity, whereas the expression of UGT1A1 increases." (PMID 38309958, 2024). "Morbid obesity decreases UGT1A1 activity, which may lead to low DBil level." (PMID 35432184, 2021). "The increase in plasma bilirubin levels observed in the present study (~10-fold) reflects the high degree of inhibition of hepatic UGT1A1 by GNUR, which decreased hepatic steatosis in our model of dietary-induced obesity." (PMID 36830621, 2023). "Fourth, the UGT1A1*28 group had higher BMI and incidence of NAFLD than the wild-type group, consistent with the finding that obesity increases incidence of NAFLD." (PMID 30619479, 2018).
pancreatic cancer (12 papers, 2017 to 2026). "Sex hormones, which are known to influence UGT1A1 activity, and differences in UGT1A1 expression between men and women, leading to differential circulating levels, might partly explain the sex differences in pancreatic cancer risk." (PMID 34206031, 2021). "Numerous studies have shown that UGT1A1 plays a crucial role in the biotransformation of the chemotherapeutic drug irinotecan, which is used to treat advanced CRC and pancreatic cancer." (PMID 39903758, 2025).
liver disease (11 papers, 2010 to 2026). "We then analyzed the possible association between HMOX1 and UGT1A1 genotypes with laboratory markers of liver disease, inflammation, or fibrogenesis." (PMID 34943103, 2021). "As bilirubin is conjugated by UGT1A1 in the liver, liver dysfunction may result in higher circulating bilirubin levels due to some underlying liver disease process and correlates with the severity of the illness." (PMID 34206031, 2021). "Many factors influence serum bilirubin levels such as smoking status, fasting status, diseases, especially diseases of the liver, which may have obscured the effects of UGT1A1*28 polymorphism." (PMID 28098838, 2017). "Since large inter-individual differences in the glucuronidation of silymarin may confound the assessment of silymarin’s efficacy in humans, we evaluated the relationship between UGT1A1 polymorphism and the metabolism and pharmacokinetics of silymarin in patients with liver disease." (PMID 28098838, 2017). "In addition, a significant difference in the metabolic ratio observed between patients with NAFLD and HCV suggests that any effect of UGT1A1 polymorphism may be obscured by a greater effect of liver disease on the pharmacokinetics of silymarin." (PMID 28098838, 2017). "In this study, we observed lower metabolic ratios in patients with NAFLD compared to those with HCV infection which raises the possibility that the influence of liver disease may mask the influence of UGT1A1*28 polymorphism on the pharmacokinetics of silymarin." (PMID 28098838, 2017). "In this work, subjects with UGT1A1 intermediate (IM) or poor (PM) metabolizer genotype-informed phenotypes were investigated to determine whether they have a higher incidence of liver disease or other biochemical parameters." (PMID 38766628, 2024). "Differences were neither found in the inflammatory parameters among patients with different HMOX1/UGT1A1 variants, nor in the severity of liver disease." (PMID 34943103, 2021). "However, the relationship between UGT1A1 polymorphism and bilirubin concentration in patients with liver disease has not been previously examined." (PMID 28098838, 2017). "Taken together, these results suggest the presence of the UGT1A1*28 allele does not contribute significantly to a large inter-subject variability in the pharmacokinetics of silybin A and silybin B which may obscure the ability to detect beneficial effects of silymarin in patients with liver disease." (PMID 28098838, 2017).
anemia (10 papers, 2010 to 2026). A reduction in the number of red blood cells, the amount of hemoglobin, and/or the volume of packed red blood cells. "A significant association was also observed between the UGT1A1 6/7 genotype and grade 3/4 anaemia (P=0.031)." (PMID 20216541, 2010). "All UGT1A1 *28/*28 patients experienced grade ≥ 2 AEs (100% vs. 69.3%; p = 0.109), with a statistically significant association in the case of febrile neutropenia (33.3% vs. 6.7%; p = 0.025), and a trend towards higher rates of anemia and diarrhea (50.0% vs. 17.3%; p = 0.053)." (PMID 41598512, 2026). "An OR of 2.15 (95% CI: 0.96–4.80) was calculated for severe (≥ 3 grade) diarrhea (I2 = 29%) and 2.69 (95% CI: 1.41–5.14) for severe (≥ 3 grade) anemia (I2 = 0%) in UGT1A1*28/*28 individuals in comparison to UGT1A1 wild‐type individuals." (PMID 40936312, 2026).
gastric cancer (10 papers, 2011 to 2025). A primary or metastatic malignant neoplasm involving the stomach. "The incidence of the UGT1A1*60 polymorphism was significantly higher in Korean gastric cancer patients (50.8%, p < 0.001) than in normal Koreans (26.0%)." (PMID 36239106, 2022). "The prevalence of the UGT1A1*28 polymorphism was lower in Korean gastric cancer patients (23.8%, p = 0.775), similar to other Korean and Asian populations (11.0%‒25%), and different from studies of Western populations (>30.0%)." (PMID 36239106, 2022). "Several studies showed that UGT1A1 polymorphisms (homozygous or double heterozygous UGT1A1*6/*28) is associated with delayed metabolism of SN-38, and this leads to enhanced irinotecan-induced toxicity in various tumors including gastric cancer." (PMID 32666389, 2020). "It is unclear whether the UGT1A1 status, single heterozygous (SH) or wild type (WT), is associated with the efficacy and toxicity of irinotecan monotherapy in advanced gastric cancer (AGC)." (PMID 32666389, 2020). "The UGT1A1 polymorphism may be useful to screen the risk population of gastric cancer, while TYMS, TUBB3 and STMN1 may be potential biomarkers for prognosis and chemotherapy guidance." (PMID 28056823, 2017). "Our findings suggest UGT1A1 polymorphisms may be useful to screen the risk population of gastric cancer and schedule the appropriate pretreatment to improve the overall survival, while TYMS, TUBB3 and STMN1 may be potential biomarkers for prognosis and chemotherapy guidance." (PMID 28056823, 2017). "The UGT1A1*6 and UGT1A9*22 genotypes showed a higher prevalence in Korean gastric cancer patients, while the prevalence of the UG1A1*28 polymorphism was lower than in normal Koreans, as has been found in other studies of Asian populations." (PMID 36239106, 2022). "For example, in the third-line treatment of gastric cancer, it was found that patients with wide type UGT1A1 had better OS, DCR and time to progress (TTP) than mutant patients." (PMID 35340156, 2022). "In summary, our study shows a unique UGT1A genotype pattern in Korean gastric cancer patients and suggests that the presence of the UGT1A1*6, UGT1A7*3 and UGT1A9*22 polymorphisms in gastric cancer patients receiving irinotecan-containing treatment was significantly associated with severe toxicity." (PMID 36239106, 2022). "In a study of 84 Japanese cancer patients, comprising 50 with colon cancer, 18 with stomach cancer, seven with ovarian cancer, seven with lung cancer, and two with other types of cancer, a genetic association between UGT1A7 and UGT1A9 polymorphisms and the UGT1A1-6 allele was reported." (PMID 40432911, 2025). "It is not clear whether the close association between irinotecan toxicity and the UGT1A1*6 polymorphism alone, but not the UGT1A1*28 polymorphism, is limited to Korean cancer patients or gastric cancer patients." (PMID 36239106, 2022). "In this study, we analyzed the frequencies of important subtypes of UGT1A1, UGT1A7, and UGT1A9 in 382 Korean gastric cancer patients." (PMID 36239106, 2022). "UGT1A1, GPX3, ADH1B, and ADH4 can serve as cross pathway regulatory nodes and can be integrated into a “metabolic immune prognostic model” in the future to optimize precision treatment strategies for gastric cancer." (PMID 41031088, 2025). "These key genes (UGT1A1, ADH4, ADH1B, CYP19A1, and GPX3) are crucial for the construction of our gastric cancer (GC) prognostic model." (PMID 41031088, 2025). "Moreover, we also investigated whether the genetic variation in UGT1A1 gene was related with the clinical characteristics of gastric cancer, which, to our knowledge, has also not been performed." (PMID 28056823, 2017).
kernicterus (10 papers, 2016 to 2024). A term used pathologically to describe BILIRUBIN staining of the BASAL GANGLIA; BRAIN STEM; and CEREBELLUM and clinically to describe a syndrome associated with HYPERBILIRUBINEMIA. "In CNS, there is a severe deficiency or complete absence of the enzyme UGT1A1, leading to very high levels of unconjugated bilirubin and, in severe cases, life-threatening complications such as kernicterus." (PMID 39456788, 2024). "When not appropriately treated, CNS-I is an early lethal condition characterized by kernicterus caused by the absence of active UDP-glucuronosyltransferase 1A1 (UGT1A1)." (PMID 30285761, 2018). "However, the regional specificity of BR toxicity can also be observed in the Gunn rat, a model of kernicterus due to a spontaneous mutation in the UGT1A1 gene, indicating that UGT1A1 may be not the reason for the CNS injury topography." (PMID 31680983, 2019). "CN-I syndrome is extremely rare and can be fatal due to kernicterus, with UGT1A1 enzyme activity in CN-I either absent or greatly attenuated." (PMID 31467903, 2019).
cholestasis (9 papers, 2014 to 2026). Impairment of the bile flow caused by obstruction within the liver, or outside the liver in the bile duct system. "Based on the current findings, it is only effective for cholestasis caused by the UGT1A1, ABCB11, and ABCC2 gene mutations." (PMID 39981091, 2025). "Studies have found that the occurrence of cholestasis was accompanied by the modulating of metabolic enzyme and transporters expression like UGT1A1, MRP2, BSEP, OATP1A1, OATP1A4." (PMID 29867509, 2018). "Our findings displayed that DNts pretreatment significantly up-regulated both mRNA and protein expressions of hepatic metabolic enzymes including Cyp2b1 and Ugt1a1 in ANIT-induced cholestasis rats." (PMID 25033983, 2014). "Consistent with this, clinical studies have shown that rifampicin, an active PXR ligand in humans, upregulates PXR activation-mediated phase II UDP-glucuronosyltransferase 1A1 (UGT1A1) and resistance-associated protein 2 (MRP2), contributing to therapeutic effects on cholestasis." (PMID 41362731, 2026). "In this study, we demonstrate that arbutin has a protective effect on α-naphthylisothiocyanate–induced cholestasis via upregulation of the levels of FXR and downstream enzymes associated with bile acid homeostasis such as Bsep, Ntcp, and Sult2a1, as well as Ugt1a1." (PMID 34926449, 2021). "UDCA showed adequate ameliorative effects on cholestasis; the treated rats manifested a 2.1-fold higher level of UGT1A1 (p < 0.01), as well as 2.2-, 2.4-, 1.2-, 2.1-, and 1.5-fold higher levels of NTCP, MDR1, BSEP, OCT1, and OATP1A2 (p < 0.05), respectively, compared with the control group." (PMID 29867509, 2018).
liver fibrosis (9 papers, 2018 to 2025). "In rats subjected to chronic CCl4-induced liver fibrosis, an alteration in the mRNA level of ugt isoforms was observed, with ugt1a1, 1a6, 2b1, and 2b2 mRNA levels being elevated, while ugt2b3, 2b6, and 2b12 mRNA levels were found to be reduced." (PMID 38790653, 2024). "As the infection time increased, liver fibrosis escalated, while liver UGT1A1 consistently exhibited a low expression, indicating impaired glucuronidation of bilirubin metabolism in mice." (PMID 38668242, 2024). "Thus, the differences in the serum ASV concentrations depending on the severity of liver fibrosis should be evaluated in the future in reference to UGT1A1 SNPs and hepatic mRNA expressions of CYP3A4 and OATP1B1." (PMID 30308053, 2018).
neonatal jaundice (9 papers, 2014 to 2024). A pigmentation disease characterized by a high level of bilirubin in the blood, causing a yellowing of the skin and other tissues of a newborn infant. "For neonatal jaundice in the Malay population, c.-3279T>G, in the promoter of UGT1A1 gene, is also recognized as a risk factor." (PMID 36128448, 2022). "It was found that reduced expression of gastrointestinal UGT1A1 was the cause of breast milk-induced neonatal jaundice." (PMID 26147428, 2015). "Oral glucose has been shown to be an effective inducer of intestinal UGT1A1 without affecting liver UGT1A1 induction and has been suggested as a convenient way to treat neonatal jaundice while continuing the benefits of breastfeeding." (PMID 32708857, 2020).
hepatoma (8 papers, 2010 to 2024). "The *1 Allele was associated with decreased transcription of UGT1A1 in transfected human hepatoma cell lines as compared to the *28 allele." (PMID 37563580, 2023). "UGT1A1, the only enzyme that conjugates with bilirubin, is significantly downregulated in malignant hepatocellular carcinoma; therefore, it can be used to predict liver cancer risk." (PMID 39625960, 2024). "We also evaluated CYP1A1, CYP1A2, NQO1, and UGT1A1 expression following leflunomide exposure in HepG2 human hepatoma cells." (PMID 20957046, 2010). "Moreover, chrysin has been found to induce UGT1A1 in the hepatoma cell line Hep G2." (PMID 29163158, 2017). "Again in non-hepatoma cell line HEK293T cells, the expression of HLP-driven UGT1A1 was significantly lower compared to the cells transfected with rSV-hUGT1A1." (PMID 33891666, 2021). "In summary, results of the current study confirm the positive effects that PPARα agonists exert on UGT1A1 expression and support a similar response of the MRP2 gene, at least in human hepatocytes and hepatoma HepG2 cells." (PMID 25147562, 2014).